PRSS23 (serine protease 23)
Diseases named in the same sentence as PRSS23 in open-access papers (continued):
Sharing a sentence is not in itself a finding about the gene and the disease.
cancer (11 papers, 2010 to 2025). A tumor composed of atypical neoplastic, often pleomorphic cells that invade other tissues. "PRSS23 has been associated with various cancers, with high expression levels typically correlating with a worse prognosis." (PMID 40278569, 2025). "The expression of PRSS23 has been associated with tumor progression in humans, the regulation of cellular proliferation, and cancer." (PMID 40278569, 2025). "Biomarkers associated with various IDHmut conditions, including the less characterized protease PRSS23, have considerable prospects for further research or clinical applications of IDHmut cancers and related diseases." (PMID 34997121, 2022). "Specifically, we characterized PRSS23 staining by comparing PRSS23 expression intensities in the nucleoplasm of cancer cells to the expression intensities in normal stromal cells and endothelial cells using the Allred immunohistochemistry score system." (PMID 22291950, 2012). "We would like to thank Dr. Jang-Yang Chang, Dr. Wayne Wen-Shiang Chang, and Dr. Ching-Chuan Kuo of National Health Research Institutes, Taiwan, for providing PRSS23 cDNA cloning primers and cancer cell lines." (PMID 22291950, 2012). "As a novel serine protease, the biological function of PRSS23 is rarely studied in cancers." (PMID 36189305, 2022). "Therefore, we first evaluated the protein expression of PRSS23 in normal and cancer tissue of stomach using the HPA web tool." (PMID 36189305, 2022). "Our data highlights that the upregulation of PRSS23/FGF2 may be critical for macrophage infiltration in pan-cancer." (PMID 36189305, 2022). "Abnormal regulation of serine protease activity could lead to pathological conditions such as cancer; in vitro assays have also proposed PRSS23 as a potential biomarker of exposure to PM2.5 and reaffirmed its contribution to cancer development." (PMID 34440450, 2021). "PRSS23 is suggested to regulate cellular proliferation and cancer." (PMID 28193179, 2017). "However, as a conserved member of the trypsin family of serine proteases, the biological function of serine protease PRSS23 remains largely unknown in cancers." (PMID 36189305, 2022). "Genes in the regulation of the insulin-like growth factor transport pathway have known functions in cancer proliferation and migration, including IGFBP5, PRSS23, SCG2, and SPP1." (PMID 35008167, 2021). "To confirm whether estrogen is indeed not able to upregulate PRSS23 expression in ERα-negative cancer cells, we treated MDA-MB-231 (ERα-negative) cells with 1 nM E2 and measured the mRNA levels of PRSS23 and pS2, with the latter serving as a positive control for estrogen responsiveness." (PMID 22291950, 2012).
cardiovascular disease (1 paper, 2022). "Exosomal PRSS23 is, e.g., involved in cardiovascular disease where the protease likely mediates Snail/alpha‐smooth muscle actin signalling." (PMID 34997121, 2022).
infection (1 paper, 2023). The state of being infected such as from the introduction of a foreign agent such as serum, vaccine, antigenic substance or organism. "At 72 h post infection (hpi), the different levels of rTS-2B/GFP titers from the cells expressing proteases were observed in the order of Tmprss9 > Cfd > Prss23 = Tmprss4 > F7 > ev, and those of rTS-GFP titers were observed in the order of Tmprss9 > Tmprss4 > F7 > ev = Cfd = Prss23." (PMID 37042750, 2023).
PRSS23 also shares sentences with these, for which no sentence is quoted: renal cell carcinoma (2 papers); acute myocardial infarction (1); adenocarcinoma (1); asthma (1); breast (1); capillary malformation (1); cardiac interstitial fibrosis (1); cervical cancer (1); chronic obstructive pulmonary disease (1); colorectal cancer (1); congenital glaucoma (1); dilated cardiomyopathy (1); end stage renal disease (1); Ewing sarcoma (1); glioma (1); Glucose intolerance (1); heart (1); leprosy (1); lung adenocarcinoma (1); lung fibrosis (1); lymph node metastasis (1); malignant pleural mesothelioma (1); Obesity (1); papillary thyroid carcinoma (1); psoriasis (1); squamous cell carcinoma (1); squamous cell lung carcinoma (1).